KHDRBS3 (KH RNA binding domain containing, signal transduction associated 3)
Description:
RNA-binding protein that plays a role in the regulation of alternative splicing and influences mRNA splice site selection and exon inclusion. Binds preferentially to the 5'-[AU]UAAA-3' motif in vitro. Binds optimally to RNA containing 5'-[AU]UAA-3' as a bipartite motif spaced by more than 15 nucleotides. Binds poly(A). RNA-binding abilities are down-regulated by tyrosine kinase PTK6. Involved in splice site selection of vascular endothelial growth factor. In vitro regulates CD44 alternative splicing by direct binding to purine-rich exonic enhancer (By similarity). Can regulate alternative splicing of neurexins NRXN1-3 in the laminin G-like domain 6 containing the evolutionary conserved neurexin alternative spliced segment 4 (AS4) involved in neurexin selective targeting to postsynaptic partners such as neuroligins and LRRTM family members. Targeted, cell-type specific splicing regulation of NRXN1 at AS4 is involved in neuronal glutamatergic synapse function and plasticity (By similarity). May regulate expression of KHDRBS2/SLIM-1 in defined brain neuron populations by modifying its alternative splicing (By similarity). Can bind FABP9 mRNA (By similarity). May play a role as a negative regulator of cell growth. Inhibits cell proliferation. (Microbial infection) Involved in post-transcriptional regulation of HIV-1 gene expression.
Synonyms: SLM-2; SALP; SLM2; T-STAR; Etle; etoile; TSTAR
Tractability: PROTAC: UniProt records ubiquitination sites on it; its protein half-life has been measured.
Gene: Protein-coding gene on chromosome 8 (135,457,456 to 135,656,722, forward strand). Ensembl gene ENSG00000131773.
Subcellular location: Nucleus
Subcellular location (Human Protein Atlas): Nucleoplasm
Pathways (Reactome):
Signal Transduction: PTK6 Regulates Proteins Involved in RNA Processing
Gene Ontology:
Molecular function: identical protein binding; protein binding; protein domain specific binding; RNA binding; nucleic acid binding
Biological process: regulation of alternative mRNA splicing, via spliceosome; regulation of mRNA splicing, via spliceosome
Cellular component: nucleoplasm; nucleus; protein-containing complex
Genetic constraint (gnomAD): Loss-of-function variants: 14 observed, 19.72 expected, observed/expected ratio (o/e) 0.71, 90% interval 0.47 to 1.11. The upper end of that interval is the gene's LOEUF score, 1.11, which puts it in group 4 of 6, group 1 being the genes least tolerant of losing a copy. Missense variants: 213 observed, 225.13 expected, observed/expected ratio (o/e) 0.95, 90% interval 0.85 to 1.06. Synonymous variants: 102 observed, 85.31 expected, observed/expected ratio (o/e) 1.2, 90% interval 1.02 to 1.41.
Homologues: Orthologues: macaque KHDRBS3 (99% identical), mouse Khdrbs3 (97% identical), rat Khdrbs3 (96% identical), guinea pig KHDRBS3 (96% identical), rabbit KHDRBS3 (92% identical), dog KHDRBS3 (90% identical), chimpanzee KHDRBS3 (90% identical), pig KHDRBS3 (86% identical), tropical clawed frog khdrbs3 (79% identical), zebrafish KHDRBS3 (61% identical), Drosophila melanogaster qkr54B (37% identical), Drosophila melanogaster qkr58E-1 (33% identical), and 6 more. Paralogues in human: KHDRBS2 (68% identical), KHDRBS1 (58% identical), QKI (32% identical), SF1 (27% identical).
Diseases named in the same sentence as KHDRBS3 in open-access papers:
KHDRBS3 is named in the same sentence as 35 diseases in open-access papers, as found by Europe PMC text mining. Sharing a sentence is not in itself a finding about the gene and the disease. The quoted sentences say what the papers report.
gastric cancer (5 papers, 2018 to 2024). A primary or metastatic malignant neoplasm involving the stomach. "They discovered that KHDRBS3 potentially plays a significant role in the development of acquired resistance in gastric cancer stem cells." (PMID 38342791, 2024). "In gastric carcinoma, KHDRBS3 expressed in CAFs directs circ_0088300 package into CAFs-derived exosomes by specifically binding to 100-200 bp sequence." (PMID 37781039, 2023). "Shi suggested that KHDRBS3 drove circ-0088300 to accelerate the metastasis of gastric carcinoma cells." (PMID 35985767, 2022). "For instance, KHDRBS3 was found to interact with FBXO32 mRNA to promote gastric cancer progression." (PMID 37848941, 2023).
breast carcinoma (4 papers, 2013 to 2023). "Given that CD44 has 9 variant exons and the regulation of the expression of these exons is complex, SALL4‐regulated KHDRBS3 expression seems to be one of the factors for CD44 variant expression in basal‐like breast cancer." (PMID 29356399, 2018). "Conversely, KHDRBS3 expression was associated with improved survival in breast cancer." (PMID 37848941, 2023). "To identify the isoform regulated by KHDRBS3 in basal‐like breast cancer, we performed reverse transcription PCR with forward and reverse primers for CD44 designed at exon 5 and 15, respectively." (PMID 29356399, 2018). "As for the stemness of basal‐like breast cancer, our KHDRBS3 overexpression experiments showed prevention of the reduction in sphere formation ability by SALL4 knockdown." (PMID 29356399, 2018). "This indicates that although other splicing factors might function to regulate CD44 alternative splicing under the control of SALL4, the SALL4 ‐ KHDRBS3 network contributes to stemness in basal‐like breast cancer." (PMID 29356399, 2018). "We showed that KHDRBS3 enhances stemness in basal‐like breast cancer." (PMID 29356399, 2018). "KHDRBS3 is upregulated by SALL4 as a splicing factor for CD44, which enhances stemness in breast cancer cells." (PMID 37848941, 2023).
glioma (3 papers, 2019 to 2022). A benign or malignant brain and spinal cord tumor that arises from glial cells (astrocytes, oligodendrocytes, ependymal cells). "A previous study showed that the combined application of KHDRBS3 can promote the transmembrane transport of Dox and induce apoptosis of glioma cells." (PMID 36064747, 2022). "The KHDRBS3 has a role in blood–tumor barrier (BTB) that severely restricts the efficient delivery of antitumor drugs to cranial glioma tissues." (PMID 33584786, 2020). "Single or combined treatment of KHDRBS3, cDENND4C, and miR-577 effectively promoted antitumor drug doxorubicin (DOX) across BTB to induce apoptosis of glioma cells." (PMID 31296839, 2019).
medulloblastoma (3 papers, 2009 to 2019). A malignant, invasive embryonal neoplasm arising from the cerebellum. "KHDRBS3 is also significantly upregulated in medulloblastoma cell lines, primary medulloblastoma tissues, breast cancer, and prostate cancer as well." (PMID 31296839, 2019). "Using these criteria, 54% (14/26), 12% (3/26) and 15% (3/20) of primary medulloblastomas showed evidence of overexpression of hsa-miR-30b, hsa-miR-30d, and KHDRBS3, respectively." (PMID 19584924, 2009). "Expression of mature hsa-miR-30b and hsa-miR-30d, as well as KHDRBS3, was analysed in cohorts of primary medulloblastoma samples, alongside four normal cerebellar samples, and data for medulloblastoma cell lines (n = 8)." (PMID 19584924, 2009). "Based on these findings, we next investigated the expression of the two mi-RNAs and KHDRBS3 in primary medulloblastomas and normal cerebellum, to further explore any roles in medulloblastoma development." (PMID 19584924, 2009). "Of these, only expression of hsa-miR-30b, hsa-miR-30d and KHDRBS3 correlated with copy number status, and all three of these transcripts also displayed evidence of elevated expression in sub-sets of primary medulloblastomas, measured relative to the normal cerebellum." (PMID 19584924, 2009). "The function(s) of KHDRBS3, hsa-miR-30b and hsa-miR-30d, and in particular any roles they may play in tumourigenesis, have not been widely investigated, and this is the first study, to our knowledge, to investigate their status in medulloblastoma." (PMID 19584924, 2009). "Our findings implicate hsa-miR-30b, hsa-miR-30d and KHDRBS3 as putative oncogenic target(s) of a novel recurrent medulloblastoma amplicon at 8q24.22–q24.23, which is independent of MYC amplification and unique to this disease." (PMID 19584924, 2009).
osteoporosis (3 papers, 2015 to 2023). A condition of reduced bone mass, with decreased cortical thickness and a decrease in the number and size of the trabeculae of cancellous bone (but normal chemical composition), resulting in increased fracture incidence. "However, the Framingham osteoporosis study found a region around KHDRBS3 as a potentially pleiotropic association with lumbar spine and femoral neck bone mineral density." (PMID 26023928, 2015).
prostate carcinoma (3 papers, 2017 to 2025). A carcinoma that arises from epithelial cells of the prostate gland. "However, CD10, KHDRBS3, PCLAF, PSMA, SIK2 and GDF15 were differentially expressed with prostate cancer progression." (PMID 39578642, 2025).
colon cancer (2 papers, 2009 to 2013). "Although one published study has demonstrated that expression of KHDRBS3 positively regulates telomerase activity in human colon cancer HCT-116 cells, further details of KHDRBS3 function and association with cancers are not clear." (PMID 19584924, 2009).
melanoma (2 papers, 2018 to 2025). A malignant, usually aggressive tumor composed of atypical, neoplastic melanocytes. "SHAP value analysis ranked RPL35, KHDRBS3, ATP6V0D1, and CRIP2 as the most important contributors to melanoma classification." (PMID 40909289, 2025).
colorectal cancer (1 paper, 2022). A primary or metastatic malignant neoplasm that affects the colon or rectum. "In colorectal cancer cells, KHDRBS3 was found to promote drug resistance by maintaining stem cell stemness." (PMID 35985767, 2022).
kidney cancer (1 paper, 2021). Primary or metastatic malignant neoplasm involving the kidney. "Additional examples among the core CT genes are CMTM1 (signaling molecule) and SLC1A6 (amino acid transporter), which are unfavorable expression markers for pancreatic and urothelial cancer, while KHDRBS3 (RNA splicing) and GLUD2 (glutamate dehydrogenase) are favorable markers for kidney cancer." (PMID 33426787, 2021).
leukemia (1 paper, 2022). A malignant (clonal) hematologic disorder, involving hematopoietic stem cells and characterized by the presence of primitive or atypical myeloid or lymphoid cells in the bone marrow and the blood. "In the human leukemia specimens, KHDRBS3 is downregulated in pro-B cell leukemia carrying MLL-AF4." (PMID 36335100, 2022).
male infertility (1 paper, 2025). The inability of the male to effect fertilization of an ovum after a specified period of unprotected intercourse. "Several studies have highlighted the importance of epigenetic regulators, including ARID4B, EZH2, CUL4, and KHDRBS3, in spermatogenesis and their association with male infertility." (PMID 40949795, 2025).
ovarian carcinoma (1 paper, 2023). A malignant neoplasm originating from the surface ovarian epithelium. "KHDRBS3 promoted xenograft tumor growth in vivo, and its downregulation induced apoptosis of ovarian cancer cells." (PMID 37848941, 2023). "Moreover, KHDRBS3 has been reported to promote glycolytic metabolism and chemoresistance to paclitaxel in ovarian cancer cells." (PMID 37848941, 2023).
cancer (15 papers, 2009 to 2025). A tumor composed of atypical neoplastic, often pleomorphic cells that invade other tissues. "Interestingly, while LPS treatment increased the proliferation and expression of the GEN1, KRIT1, CENPF, CPLANE1, STYK1, and KHDRBS3 genes, it decreased the expression of the cancer associated LOC610994, Gpatch4, SLC7A1, ATP13A2, and TEX45 genes in tumor enteroids." (PMID 35884586, 2022). "A recent pivotal study revealed that KHDRBS3 plays an important role in regulating drug resistance in cancer cell." (PMID 37848941, 2023). "Consistent with clinical outcomes in other cancers, high levels of KHDRBS3 predicted a poor prognosis for HCC patients." (PMID 37848941, 2023). "Sam68 (KHDRBS1), a homolog of KHDRBS3, was found to be co-expressed with cancer-related genes in the genome-wide analysis." (PMID 35884586, 2022). "Sam68 (KHDRBS3) exhibited a prognostic significance in various malignancies and was elevated in cancer cell lines." (PMID 35884586, 2022). "CD44v overexpression prevented a reduction in the sphere formation ability by KHDRBS3 knockdown, indicating that CD44v is positively involved in cancer stemness." (PMID 29356399, 2018). "KHDRBS3 upregulation induced 5-FU multidrug resistance and cancer stem cell features." (PMID 41440014, 2025). "In recent years, growing scientific researches have focused on the importance of KHDRBS3 in cancer." (PMID 37848941, 2023). "KHDRBS3 promoted aerobic glycolysis and resistance to paclitaxel in cancer cells." (PMID 37848941, 2023). "Our results suggest the possible roles of GEN1, KRIT1, CENPF, STYK1, and Sam68/KHDRBS3 in promoting cancer cell proliferation, and these findings may provide a potential therapeutic target to control mast cell malignancy." (PMID 35884586, 2022). "Furthermore, previous studies have shown that KHDRBS3 promotes cancer cell proliferation." (PMID 37848941, 2023). "To validate the RNA-seq analysis, we selected seven representative genes on the basis of their relevance for HGSOC (PAX8, EGFR) and other cancers (GATA6, RBM47, KHDRBS3), or for their involvement in the DDR pathway (ATRIP, POLH)." (PMID 37202753, 2023). "The core CT genes include CMTM1, CT83 (CXorf61), EZHIP (CXorf67), DCAF4L2, KHDRBS3, LEMD1, PIWIL1, and SPATA6, which contribute to cancer progression and metastasis." (PMID 33426787, 2021). "However, the function of KHDRBS3 on cancer stemness remained unknown." (PMID 29356399, 2018). "For KHDRBS3, the KO efficiency was higher, and this gene was not scored to be essential in pan-cancer cell lines (DepMap Public 23Q2)." (PMID 38132164, 2023). "This study revealed that SALL4 regulates CD44v expression via KHDRBS3 for stemness, which might contribute to understanding of the function of SALL4 on cancer stemness." (PMID 29356399, 2018).
tumor (11 papers, 2009 to 2025). "Even though LPS treatment failed to diminish the expression of genes involved in proliferation and malignancy such as GEN1, KRIT1, CENPF, STYK1, and Sam68/KHDRBS3, it did reduce the expression of numerous genes implicated in tumor growth." (PMID 35884586, 2022). "Additionally, a marginal correlation was also observed in PTEN and KHDRBS3 markers in biopsy grade group 2 when comparing to Likert score, with their association to more aggressive tumours discussed earlier." (PMID 39578642, 2025). "Overexpression of KHDRBS3 promoted tumor growth, while KHDRBS3 silencing inhibited tumor progression." (PMID 37848941, 2023). "To explore the role of KHDRBS3 in tumor growth in vivo, we established the subcutaneous xenograft tumor model and monitored the tumor growth." (PMID 37848941, 2023). "Murine xenograft tumor models were constructed to study the role of KHDRBS3 on tumor growth in vivo." (PMID 37848941, 2023). "A crucial NF-κB regulator, Sam68 (KHDRBS3), was also observed to be elevated in LPS-treated tumor enteroids, along with the genes GEN1, KRIT1, CENPF, and STYK1." (PMID 35884586, 2022). "Single or combined treatment of KHDRBS3, cDENND4C, and miR-577 effectively promote the anti-tumor effect of Dox." (PMID 31296839, 2019). "In this study, KHDRBS3 was upregulated in HCC tumor tissues and predicted a poor prognosis." (PMID 37848941, 2023). "Moreover, KHDRBS3 expression was higher in tumor tissues compared to normal tissues in the three GEO datasets." (PMID 37848941, 2023). "The tumor tissue also revealed an increase in CLK2 mRNA expression, whereas the KHDRBS3 mRNA expression was lower, compared to normal tissue." (PMID 38132164, 2023). "Overexpression of KHDRBS3 promoted proliferation of HCC cells in vitro and tumor growth in vivo and enhanced cell resistance to doxorubicin, whereas silencing of KHDRBS3 reversed these effects." (PMID 37848941, 2023). "Knockdown of KHDRBS3 exhibited a carcinostatic effect in HCC and impeded proliferation and tumor growth, reduced glycolysis, enhanced cell sensitivity to doxorubicin, and induced apoptosis." (PMID 37848941, 2023). "However, CD10, KHDRBS3, PCLAF, PSMA, SIK2 and GDF15 were differentially expressed with PCa progression, emphasising their roles in promoting tumour growth, invasion and metastasis." (PMID 39578642, 2025). "High-level expression of KHDRBS3, equivalent to levels observed in an 8q24.22–q24.23 amplified cell line, was also observed in a sub-set of primary tumours and other cell lines, but was not restricted to the 8q24.22–q24.23 amplified cell lines." (PMID 19584924, 2009).
KHDRBS3 also shares sentences with these, for which no sentence is quoted: cardiomyopathy (2 papers); heart failure (2); Anxiety (1); dilated cardiomyopathy (1); endometriosis (1); epilepsy (1); heart disease (1); hepatocellular carcinoma (1); Hydrocephalus (1); Infertility (1); invasive breast carcinoma (1); ischemic cardiomyopathy (1); metastatic disease (1); neurodegenerative disease (1); Osteopenia (1); Pleural effusion (1); prostate tumor (1); psychiatric disease (1); respiratory diseases (1); schizophrenia (1).